GSK3B (glycogen synthase kinase 3 beta)
Diseases named in the same sentence as GSK3B in open-access papers (continued):
Sharing a sentence is not in itself a finding about the gene and the disease.
esophageal cancer (25 papers, 2011 to 2025). A primary or metastatic malignant neoplasm involving the esophagus. "In an attempt to determine the underlying signaling mechanism by which t-DARPP regulates β-catenin, we demonstrated that t-DARPP overexpression in gastric and esophageal cancer cells was associated with increased phosphorylation of GSK-3β." (PMID 21447180, 2011). "Previous studies have shown that GSK3β functions in the phosphorylation-dependent activation of STAT3 and that inhibition of GSK3β attenuates the progression of gastric and esophageal cancers by suppressing STAT3 activity." (PMID 38318525, 2024). "FAM83D was reported to regulate the EMT process of esophageal cancer cells through the Akt/GSK‐3β/signaling pathway." (PMID 35796646, 2023). "In esophageal cancer, KNSTRN expression is positively correlated with that of GSK-3β, which is associated with a poor prognosis." (PMID 36845017, 2023). "Results showed reductions in p-AKT, p-GSK3β, and active-β-catenin, whereas GSK3β levels increased in PCDH20 overexpressing esophageal cancer cells." (PMID 36248995, 2022). "Knockdown of MTAP can activate the GSK3β/Slug/E-cadherin axis and promote migration and invasion in esophageal cancer." (PMID 35541910, 2022). "Active β-catenin, p-AKT, and p-GSK3β levels were restored in MAP3K9 overexpressing esophageal cancer cells after simultaneous stable expression of PCDH20." (PMID 36248995, 2022). "Collectively, these data revealed a possible mechanism by which apatinib inhibited esophageal cancer progression by suppressing the VEGFR2/Akt/GSK-3β/β-catenin pathway." (PMID 32514243, 2020). "Furthermore, knockdown of MTAP leads to activation of the glycogen synthase kinase 3 beta (GSK3β)/Slug/E-cadherin axis to promote migration and invasion of esophageal cancer cells." (PMID 41439984, 2025). "In esophageal cancer, TDO2 can upregulate IL-8 through the AKT/GSK3β pathway, thereby inducing polarization of M2 macrophages in ESCC." (PMID 38887298, 2024). "The LCN2/LOXL2/MMP9 complex remodels the ECM and activates the FAK/AKT/GSK3β signalling pathway to enhance SPOCK1 expression, promoting the migration and invasion of oesophageal cancer cells." (PMID 37753805, 2023). "Therefore, LCN2/LOXL2/MMP9 activated the FAK/AKT/GSK3β signalling pathway to enhance SPOCK1 expression and remodel the ECM, thus promoting the migration and invasion of oesophageal cancer cells." (PMID 37753805, 2023). "Additionally, treatment with UA or PTX enhanced the protein levels of GSK and p-GSK-3β, and combining the treatments induced markedly greater expression of GSK and p-GSK-3β protein in esophageal cancer cells." (PMID 34768915, 2021). "In esophageal cancer, the 5-year survival rate of high expression of PRR11 was significantly lower than that of the low expression group, which may be related to the interaction of PRR11 with destructive complexes (APC, GSK-3β and AXIN2) to activate the Wnt/β-catenin pathway." (PMID 34659555, 2021). "Treatment with wortmannin resulted in a dose-dependent reduced phosphorylation of AKT (p-AKT) and its downstream target GSK3β (p-GSK3β), but not total AKT or GSK3β, in four esophageal cancer cell lines, KYSE150, HKESC-1, KYSE270, and T.Tn." (PMID 25344912, 2014).
injury (24 papers, 2014 to 2025). Damage inflicted on the body as the direct or indirect result of an external force, with or without disruption of structural continuity. "miR-542-3p can target PTEN, and it can trigger the AKT/GSK3β/β-catenin pathway by targeting PTEN expression to reduce CORT-induced nerve injury (P < 0.05)." (PMID 40043208, 2025). "In this study, we explored neuroprotection of hydrogen‐rich medium through activation of the miR‐21/PI3K/AKT/GSK‐3β pathway in an in vitro model of traumatic brain injury." (PMID 32108985, 2020). "CAY10594 administration strongly blocked GSK-3β (Serine 9)/JNK phosphorylation in the APAP-induced acute liver injury model." (PMID 31076618, 2019). "Our data also suggested that NF-κB and CREB mediated mechanisms are the prominent pathways involved in the protective effects of GSK-3β inhibition in the CLP-induced liver injury." (PMID 25525303, 2014). "The regulation of GSK3-β and Akt via D2R could be a novel therapeutic approach following brain injury." (PMID 33430188, 2021). "In the previous study, our group demonstrated that MenSCs could inactivate GSK-3β in order to promote the repair of damaged lung tissue in acute lung injury." (PMID 29740283, 2018). "Moreover, GSK-3β blockade significantly reduced hepatic apoptotic cell death in response to D-galactosamine/LPS-induced liver injury or ischemia/reperfusion (I/R) injury, respectively." (PMID 25525303, 2014). "Hence, we investigated whether the mechanism of liraglutide involved in protecting against neonatal HI brain injury is related to the activation of the PI3K/Akt/GSK3β signaling pathway." (PMID 32082121, 2019). "Therefore, GSK3β-mediated eIF2Bε activation enhances the recycling of eIF2 for further rounds of translational initiation, constituting a critical regulatory mechanism to control the intrinsic regenerative ability of RGCs after nerve injury." (PMID 26974342, 2016). "In lipopolysaccharide-induced acute lung injury in mice, TLB treatment effectively inhibited the oxidative stress and inflammatory damage via the AMPK/GSK-3β/Nrf2 and NF-κB pathways." (PMID 38913606, 2024). "Xanthohumol activates the AMPK/GSK3β-Nrf2 axis and dampens the Txnip/NLRP3 inflammasome and NF-κB, which reduces oxidative stress and ameliorates LPS-induced acute lung injury." (PMID 34366838, 2021). "Molecular pathways such as cAMP, MAPK, JAK/STAT, ATF3/CREB, BMP/SMAD, AKT/mTORC1/p70S6K, PI3K/AKT, GSK-3β/CLASP, BDNF/Trk, Ras/ERK, integrin/FAK, RhoA/ROCK/LIMK, and POSTN/integrin are activated after nerve injury and are considered significant players in axonal regeneration." (PMID 36551942, 2022).
colitis (23 papers, 2009 to 2025). Inflammation of the colon. "Importantly, we show that pharmacological targeting of GSK3 or genetic deletion of Gsk3b corrects T lymphocyte survival and prevents severe early-onset colitis in Gimap5-deficient mice." (PMID 29382851, 2018). "This study reported improved experimental colitis in LGR4 mutant mice through inhibition of glycogen synthase kinase 3 beta (GSK-3β), indicating an important role of LGR4 in inflammatory bowel disease (IBD) recovery." (PMID 41333132, 2025). "In other DSS-dependent UC models, colitis was similarly attenuated under conditions involving GSK3β inactivation, e.g., in GSK3 inhibitor- (LiCl, SB216763, 6-(methylsulfinyl)hexyl isothiocyanate), P2Y2 receptor agonist-, and CO-treated or CD97 transgenic mice." (PMID 39125833, 2024). "Conclusively, TRPM8 inhibits SP release from primary sensory neurons by inhibiting the interaction between PKAca and GSK-3β, thereby inhibiting the role of SP in promoting colonic epithelial apoptosis and relieving colitis." (PMID 38280896, 2024). "L-theanine suppressed the expression levels of TNF-α, IL-1β, IL-6, iNOS, and COX-2 in DSS-induced colitis, and relieved phosphorylation of GSK-3β and Akt/mTOR in Cd-induced ICR mice." (PMID 39572022, 2024). "The absence of Pygo2 attenuated the development of MAT lesions in Il‐10−/− mice by promoting the differentiation of adipocytes, leading to the amelioration of colitis partly through the Axin2/GSK3β pathway." (PMID 35707871, 2022). "Our results demonstrated that melatonin-mediated MT2 inhibits Aeromonas-goblet cell interactions to restore the level of MUC2 production via LPS/TLR4/MyD88/GSK-3β/ROS/NF-κB loop, further improving colitis in SD mice." (PMID 35355860, 2022). "Inhibiting of Pygo2 attenuated the development of MAT lesions in Il‐10−/−mice by promoting the differentiation of adipocytes, reducing inflammation, and leading to the amelioration of colitis partly through the Axin2/GSK3β pathway." (PMID 35707871, 2022). "Overall, our study revealed that MT2-mediated MT suppressed Aeromonas coupling with goblet cells and restored MUC2 depletion by inhibiting the TLR4/MyD88/GSK-3β/β-catenin/ROS/NF-κB loop, ultimately improving SD-induced colitis in mice." (PMID 35355860, 2022). "In another study, geraniol improved experimental colitis partly via its antioxidant, anti-inflammatory, and immunosuppressive potentials, possibly by modulating the Wnt/GSK-3β/β-catenin, p38MAPK, NF-κB, and PPARγ signaling pathways." (PMID 33053761, 2020). "The decreased Akt expression and increased GSK-3β expression in colitis were also reversed by fortunellin." (PMID 29472916, 2018). "To confirm the in vivo data regarding regulation of colitis and involvement of CO and GSK-3β, we did some in vitro experiments with U937 monocytes and MLN cells." (PMID 24349609, 2013). "Results indicating the role of CO in inhibition of DSS-induced colitis are mediated through inhibition of GSK-3β activation." (PMID 24349609, 2013). "We found that DSS induced colitis significantly shortened colon length and, inhalation of CO or LiCl administration significantly recovered DSS effects, suggesting beneficial effects of CO on DSS-induced colitis where inhibition of GSK-3β is involved." (PMID 24349609, 2013). "In this study, we showed that DSS-induced colitis is attenuated by CO-mediated inhibition of GSK-3β signaling in experimental mice model." (PMID 24349609, 2013). "Together, our findings indicate that CO attenuates DSS-induced colitis via inhibition of GSK-3β signaling in vitro and in vivo." (PMID 24349609, 2013). "To examine the in vivo effects of CO or GSK-3β inhibitor (LiCl) on survival of DSS-induced colitis mice, we inhaled mice with CO (250 ppm) for 4 h or administrated LiCl (200 mg/kg, i.p.)on daily basis to mice for more 6 days." (PMID 24349609, 2013).
colitis (continued). "However, single studies reported increased GSK3β activity in colitis-limiting approaches, e.g., increased p-GSK3β-Tyr216 levels following injection of the peroxisome proliferator-activated receptor (PPAR-)γ modulator GED-0507-34 Levo." (PMID 39125833, 2024). "The increase in Pygo2 may be related to mesenteric adipocyte poor differentiation and inflammatory features of CD, and Pygo2 inhibition could alleviate CD‐like colitis by improving mesenteric lesions by regulating the Axin2/GSK3β pathway." (PMID 35707871, 2022). "Previous studies have showed that wogonin can be used to treat colitis by inducing the expression of transcription factor HIF-1α through the protein kinase B/glycogen synthase kinase β (AKT/GSK3β) signaling pathway to increase interleukin 10 (IL-10) production." (PMID 35399629, 2022). "Data from a study focusing on spontaneous resolution of inflammation in a murine trinitrobenzene sulfonic acid-induced colitis model revealed that colitis-induced secretion of IL-13 led to the inactivation (i.e., Ser9 phosphorylation) of GSK3β via the STAT6-driven activation of p38." (PMID 32231133, 2020). "Importantly, conditional deletion of Gsk3β in CD4+ T cells was sufficient to prevent the development of colitis." (PMID 29382851, 2018). "Inhibition of GSK-3β signaling has been reported to reduce experimental colitis in rat." (PMID 24349609, 2013). "Importantly, this is the first report that investigated the molecular mechanisms mediated the novel effects of CO via inhibition GSK-3β in DSS-induced colitis model." (PMID 24349609, 2013). "Similarly, to determine the in vivo effects of CO or GSK-3β inhibitor (LiCl) on body weight of DSS-induced colitis mice, CO (250 ppm) inhalation for 4 h or administrated LiCl (200 mg/kg, i.p.)on daily basis was performed." (PMID 24349609, 2013). "Therefore, we suggest that the therapeutic effects of CO on DSS-induced colitis result from the inhibition of GSK-3β and NF-κB activation." (PMID 24349609, 2013). "Importantly, GSK3β is central to the promotion of inflammation in various inflammatory diseases including colitis and arthritis." (PMID 19274078, 2009). "Therefore, in our study, a large number of in vivo and in vitro experiments have been demonstrated that melatonin-mediated MT2 inhibits aeromonas-goblet cell interactions to restore the level of MUC2 production via the LPS/TLR4/MyD88/GSK-3β/ROS/NF-κB loop, further improving colitis in SD mice." (PMID 35355860, 2022). "Some studies reported that the expression of IL-10 in the colon was reduced in mice with DSS-induced colitis, and Wogonin enhanced IL-10 production by inducing transcript factor HIF-1α expression via the AKT/GSK3β signal pathway." (PMID 36176442, 2022). "MA is able to inhibit the activation of γδT17 cells through PPARγ–PTEN/Akt/GSK3β/NFAT pathway, reduce the level of IL-17 in colon tissues of colitis mice, and ameliorate DSS-induced colitis in mice." (PMID 32929062, 2020). "In summary, these findings reveal that MA inhibits the activation of γδT17 cells through PPARγ–PTEN/Akt/GSK3β/NFAT pathway, which contributes to the amelioration of colitis." (PMID 32929062, 2020). "In summary, our data demonstrate that CO decreases inflammatory responses via inhibition of GSK-3β and pro-inflammatory cytokines in DSS-induced colitis." (PMID 24349609, 2013). "To know the effect of CO on GSK-3β and DSS-induced colitis, we inhaled mice with CO (250 ppm) for 4 h or administrated LiCl (200 mg/kg, i.p.)on daily basis to mice for more 4 days." (PMID 24349609, 2013). "GSK-3β inhibitory peptide (IAGIP) is specifically activated by activated inhibitory kappa B kinase (IKK), and its therapeutic effects have been demonstrated in a mouse model of colitis." (PMID 35055183, 2022).
colitis (continued). "Lithium, a GSK-3β inhibitor and autophagy modulator, has demonstrated pro-repair and anti-inflammatory effects in preclinical gut models, including enhanced mucosal regeneration after DSS colitis and attenuation of experimental colitis via microbiota- and Treg-dependent mechanisms." (PMID 41154835, 2025). "In our study, we found that CO and GSK-3β inhibitor significantly improved the survival of DSS-treated mice by increasing body weight, colon length and histological parameters, suggesting that CO inhalation improved experimental colitis by inhibition of GSK-3β signaling." (PMID 24349609, 2013).
endometrial cancer (23 papers, 2013 to 2025). Primary or metastatic malignant neoplasm involving the endometrium (mucous membrane that lines the endometrial cavity). "Altogether, these data demonstrated that GSK3β inhibition caused endometrial cancer cell cycle arrest at different stages during G2/M phase, possibly due to varying genetic make-up and cell context differences." (PMID 23941783, 2013). "Our results indicate that GSK3β activity is associated with endometrial cancer tumorigenesis and that its pharmacologic inhibition reduces cell proliferation and tumor growth." (PMID 23941783, 2013). "Furthermore, 46% of the CTNNB1 mutations in endometrial cancer were reported to be immediately phosphorylated by glycogen synthase kinase-3 (GSK-3β)." (PMID 34836311, 2021). "Thus, GSK3β activity is associated with endometrial cancer tumorigenesis and its pharmacologic inhibition reduces cell proliferation and tumor growth." (PMID 23941783, 2013). "Mechanistically, RNF144B can stabilize the phosphorylation level of GSK3β downstream signaling molecules, and knockdown of the RNF144B gene in endometrial cancer cells inactivated GSK3β, leading to inhibition of cell proliferation." (PMID 40756570, 2025). "In summary, our results demonstrated that FBXL16 promoted MPA resistance of Ishikawa cell by PP2AB55α interaction and AKT1/GSK3β/cyclin D1 pathway in endometrial carcinoma, while knockdown of FBXL16 can reverse the MPA resistance of Ishikawa." (PMID 36106050, 2022). "Metformin treatment was able to reduce significantly GSK3β (Ser9) phosphorylation, suggesting that metformin can affect both β-catenin expression and stability in endometrial cancer cells." (PMID 33946426, 2021). "Positive correlations between LSD1 and GSK3β expression were also identified in ovarian (r = 0.39, P < 0.05) and endometrial cancer (r = 0.4, P < 0.0001) specimens." (PMID 29593255, 2018). "A proximity ligation assay (PLA) was performed to identify the interactions between LSD1 and GSK3β in formalin-fixed, paraffin-embedded endometrial cancer specimens." (PMID 29593255, 2018). "GSK3B in Cluster 2 may be affected by ancient positive selection and positive selection in the European population, which may be especially associated with incidence rate differences of endometrial cancer and basal cell carcinoma between African and European populations." (PMID 28445522, 2017). "Herein, we demonstrated the role of GSK-3β in endometrial cancer (EC) and identified new therapeutic targets." (PMID 27050373, 2016). "Recently, active AKT has been implicated in the stabilization of β-catenin through the phosphorylation of GSK-3β, further leading to the transactivation of Slug, which was increased by β-catenin in endometrial cancer cell lines." (PMID 26967563, 2016). "In multiple human endometrial cancer cell lines, attenuating GSK3β activity by biological agents or lentiviral-mediated genetic knock-down, significantly inhibited cell growth." (PMID 23941783, 2013). "Taken together, these data demonstrate that reduced GSK3β activity inhibits endometrial cancer cell growth through both cytostatic and cytotoxic mechanisms, while minimally affecting that of the normal endometrial epithelial cells." (PMID 23941783, 2013). "In this study, we tested the importance of GSK3β inhibition in endometrial cancer cell lines and in vivo models." (PMID 23941783, 2013). "Here we showed that LiCl treatment of human endometrial cancer cell lines resulted in an elevated phospho-serine 9 level, indicating lithium inhibits GSK3β in these cells." (PMID 23941783, 2013). "In summary, our results support GSK3β inhibition as a potential therapeutic approach to treat endometrial cancer." (PMID 23941783, 2013). "Treatment of AN3CA endometrial cancer cells with GSK3β inhibitors also increased sensitivity to paclitaxel, a chemotherapeutic mitotic inhibitor commonly prescribed to endometrial cancer patients." (PMID 23941783, 2013).